CD68 (CD68 molecule)
Diseases named in the same sentence as CD68 in open-access papers (continued):
Sharing a sentence is not in itself a finding about the gene and the disease.
Wilms tumor (4 papers, 2013 to 2024). An embryonal neoplasm characterized by the presence of epithelial, mesenchymal, and blastema components. "The macrophage marker CD68 exhibited the highest median value in ganglioneuroblastoma and lowest in nephroblastoma, respectively." (PMID 31922656, 2020). "The macrophage marker CD68 showed highest values in ganglioneuroblastoma, with lowest levels in nephroblastoma." (PMID 31922656, 2020). "Tissue microarray sections of 124 Wilms tumor cases obtained from the Cooperative Human Tissue Network were stained with CD68, a macrophage marker using standard immunohistochemical techniques and quantified using digital image processing techniques." (PMID 23514200, 2013). "However, CD68 median values were highest in ganglioneuroblastoma and lowest in nephroblastoma when expressed by either method." (PMID 31922656, 2020). "In contrast to all other indications, nephroblastoma showed the three cases with highest PD‐L1 density z‐scores with similar TIL density z‐scores range, while the 21 cases with lowest PD‐L1 density z‐scores correlated with lowest TIL and CD68 density z‐scores." (PMID 31922656, 2020).
abscess (3 papers, 2018 to 2025). An inflammatory process characterized by the accumulation of pus within a newly formed tissue cavity which is the result of a bacterial, fungal, or parasitic infection or the presence of a foreign body. "Immunostaining for CD68 revealed a reduction in the number of macrophages present in the inflammatory abscess upon inhibition of p110α signalling with BYL719 treatment." (PMID 40272400, 2025). "A notable decrease in the number of CD68-positive cells was observed in the inflamed abscess region of Pik3caRBD/– mice." (PMID 40272400, 2025).
acromegaly (3 papers, 2022 to 2025). Acromegaly is an acquired disorder related to excessive production of growth hormone (GH) and characterized by progressive somatic disfigurement (mainly involving the face and extremities) and systemic manifestations. "Our results indicate a presurgical SRL therapy interplay with TICs in somatotroph adenomas and show that the CD68+/CD8+ ratio is a biomarker for treatment resistance in SRL‐naïve patients." (PMID 40789673, 2025). "For example, it has been reported that CD68+ macrophage infiltration was higher than that in corticotroph adenomas and densely granulated somatotroph adenomas." (PMID 36361871, 2022). "In conclusion, our findings offer valuable insights into the interplay between somatotroph adenoma SRL therapy and the immune microenvironment, including the identification of the CD68+/CD8+ ratio as a potential biomarker for treatment resistance in SRL‐naïve patients." (PMID 40789673, 2025). "In this study, we aim to investigate the number of somatotroph adenoma infiltrating immune cells (CD68+ macrophages, CD138+ and CD8+ lymphocytes) in acromegaly patients naïve to medical therapy before surgery and in patients pretreated with SRL before surgery." (PMID 40789673, 2025).
amyotrophic lateral sclerosis (3 papers, 2015 to 2023). Amyotrophic lateral sclerosis (ALS) is a neurodegenerative disease characterized by progressive muscular paralysis reflecting degeneration of motor neurons in the primary motor cortex, corticospinal tracts, brainstem and spinal cord. "Minocycline inhibits the expression of CD68, cell surface markers of M1 polarized microglia, and inflammatory cytokines (IL-1β and TNF-a) both in vitro and in an animal model of amyotrophic lateral sclerosis." (PMID 28790417, 2017).
atopic dermatitis (3 papers, 2023 to 2025). "Additionally, we observed that CD68+/TRPV1+ cells increased in human atopic dermatitis tissue." (PMID 39257398, 2024). "Specifically, costaining of atopic dermatitis biopsies for the human monocyte marker, CD68, and GLUT3 revealed numerous CD68+GLUT3+ double-positive cells in the papillary dermis of the affected tissues (arrows)." (PMID 37721853, 2023).
autoimmune disease (3 papers, 2014 to 2024). A disorder resulting from loss of function or tissue destruction of an organ or multiple organs, arising from humoral or cellular immune responses of the individual to their own tissue constituents. "In this respect, increased numbers of CD14-expressing monocytes, CD68 or CD163-expressing macrophages, CD1c or CD11c-expressing myeloid dendritic cells have been documented in different autoimmune diseases." (PMID 24740301, 2014).
Autoimmunity (3 papers, 2018 to 2022). The occurrence of an immune reaction against the organism's own cells or tissues. "Findings also included marked increases in CD68+ perivascular macrophages and monocytes, suggesting the possibility of monocyte infiltration, which is one of the markers considered when autoimmunity is suspected in MS and EAE models." (PMID 30483058, 2018).
brain infarcts (3 papers, 2005 to 2022). "Expression of NgR1, TROY and LINGO-1 was found in CD68+ cells (i.e. macrophages, microglia, and a subset of DCs) within chronic, active demyelinating MS lesions and ischemic lesions of acute and old cerebral infarctions." (PMID 21906273, 2011).
cholangiocarcinoma (3 papers, 2016 to 2024). A carcinoma that arises from the intrahepatic biliary tree (intrahepatic cholangiocarcinoma) or from the junction, or adjacent to the junction, of the right and left hepatic ducts (hilar cholangiocarcinoma). "High levels of CD68 were associated with a poorer PFI in cholangiocarcinoma (CHOL), LIHC, and STAD and a better DFI in CESC." (PMID 35550532, 2022).
chronic endometritis (3 papers, 2022 to 2025). A non-granulomatous or granulomatous chronic inflammation of the endometrium. "Spatial phenotyping demonstrated that the highest number of CD68+ macrophages in patients with moderate and severe chronic endometritis accumulated in areas containing MCs." (PMID 41511322, 2025). "A study on chronic endometritis has shown abundant immune cells in the endometrium and an increase in CD83+ mature DCs, CD68+ macrophages, CD8+ T cells, and Foxp3+ Treg cells; these results might be reasonable for impaired endometrial receptivity and recurrent pregnancy failures." (PMID 36686483, 2022).
chronic tonsillitis (3 papers, 2015 to 2023). "Our study is focused on the expression of CD68 and the estimation of proinflammatory cytokines in children’s patients with chronic tonsillitis secondary to vitamin D supplementation." (PMID 37198277, 2023). "We aimed in this study to assess the potential effect of serum vitamin D levels in children’s patients with chronic tonsillitis based on the histological, immunohistochemical study of CD68, and the estimation of proinflammatory cytokines." (PMID 37198277, 2023). "In conclusion, our study has seen an association between vitamin D intake and the levels of TNF-α, some interleukins, and CD68 expression in children with chronic tonsillitis." (PMID 37198277, 2023). "Single-cell and spatial maps confirmed that CD68+ cells were correlated with the enhanced Granzyme B expression and CD3+ cells exhibited enrichment of CD4+ phenotype in chronic tonsillitis." (PMID 34045665, 2021).
colorectal adenoma (3 papers, 2016 to 2022). An adenoma that arises from the colon or rectum. "Moreover, the detection of CD68+ polyP-expressing mast cells could represent a potential prognostic marker in colorectal adenomas and/or carcinomas." (PMID 29543850, 2018). "Therefore, the detection of CD68+ polyP-expressing cells rather than CD68+ mast cells could be used as a potential prognostic tool for colorectal adenoma or adenocarcinoma." (PMID 29543850, 2018).
contact dermatitis (3 papers, 2017 to 2023). An inflammatory skin condition caused by direct contact between the skin and either an irritating substance or an allergen. "We believe that our model triggered a response akin to contact dermatitis or the acute phase of AD, as evidenced by the heightened presence of macrophages (CD68+) and mast cells (TB+)." (PMID 38139083, 2023). "In an experimental model of contact dermatitis for example, dexamethasone reduced the number of CD68+ macrophages." (PMID 29125588, 2017). "Expression of CD68 and CD4 was greatly enhanced in response to stimulation by OXA; however, treatment with ghrelin drastically attenuated the secretion of CD68 and CD4, implying a reduced severity of contact dermatitis in mice." (PMID 30718736, 2019).
crescentic glomerulonephritis (3 papers, 2016 to 2023). A histopathologic term for a pattern of diseases characterized by extensive crescent formation in the glomeruli; patients present clinically with rapid deterioration of renal function, and possible progression to end-stage renal failure within weeks or months. "Histological measures of disease showed that crescentic glomerulonephritis was more severe in both groups of C5‐sufficient recipients, compared with both groups of C5‐deficient recipients, as indicated by more crescents and CD68+ macrophages within glomeruli." (PMID 27235854, 2016). "It is well known that CD68-positive macrophage infiltration in glomeruli is a major mediator in the pathogenesis of progressive glomerular injury for crescentic glomerulonephritis patients." (PMID 37231123, 2023). "In patients with crescentic glomerulonephritis, numerous CD68+ macrophages were identified in acute inflammatory lesions such as cellular crescents, but few CD68+α-SMA+ cells were evident." (PMID 27906172, 2016). "In addition, it was suggested that RAS activation induces CD68-positive macrophages and promotes crescent formation in a rat model of crescentic glomerulonephritis." (PMID 37231123, 2023).
dendritic cell tumor (3 papers, 2021 to 2025). A dendritic cell tumor develops from the cells of the immune system. "FRCT has a similar histomorphology to other dendritic cell tumors with a rather distinct immunophenotype including expression of SMA, desmin, and CD68 as well as cytokeratin, which separates it from the others." (PMID 34514557, 2021). "The 5th edition of the WHO Classification of Hematolymphoid Tumors subcategorizes the dendritic cell neoplasms under the spectrum of histiocytic/dendritic cell neoplasms based on their histogenesis and their distinct immunophenotypic profile (positive for CD45, CD4, CD68, CD163, and lysozyme)." (PMID 39592527, 2024).
Dermatofibromas (3 papers, 2020 to 2025). "Dermatofibromas consist of dermal fibroblasts and histiocytes with FXIIIA, CD163, and CD68 positivity, whereas." (PMID 41446319, 2025). "Immunohistochemistry (CD68-, CD10-, and Factor XIIIa-positive; CD34-negative) distinguished dermatofibroma from dermatofibrosarcoma protuberans, which shows deeper infiltration and CD34 positivity." (PMID 40981342, 2025).
diabetic foot ulcer (3 papers, 2022 to 2023). "For example, high levels of CD68 expression have been observed in diabetic foot ulcers, and leucocyte infiltration has been reported in chronic wounds." (PMID 35453606, 2022). "Right: Immunostaining for CD68 (green) and Gas6 (red) in diabetic foot ulcer." (PMID 38127424, 2023). "Real-Time Polymerase Chain Reaction: RT-PCR for the gene expression of CD68, CD86, CD206, CD40, IL-6, IL-1β, and TNF-α revealed increased relative gene expression (normalized to housekeeping gene 18S) in diabetic foot ulcer tissues compared to control tissues." (PMID 36362563, 2022). "To validate these findings, we stained sections of non-diabetic foot wounds and diabetic foot ulcers with Abs against Gas6 and CD68, a macrophage marker." (PMID 38127424, 2023).
disc degeneration (3 papers, 2008 to 2025). "In human disc tissues of fetuses, infants, and adolescents, CD68+ macrophages do not exist; however, they are found to be present in the nucleus pulposus of all subjects with morphologic signs of disc degeneration." (PMID 37220462, 2023). "In contrast, some CD68-positive cells were seen in the NP of all discs showing disc degeneration, but the morphology of these cells was no different from that of the cells normally found here." (PMID 18673547, 2008).
diverticulitis (3 papers, 2009 to 2022). An infection that develops in the diverticula of the intestinal tract. "Paraffin embedded tissue samples from non-inflamed and inflamed colon of IBD patients and from diverticulitis patients were immunohistochemically stained for dectin-1 and related to CD68 macrophage staining." (PMID 19915667, 2009). "Additionally, recent evidence from the histopathology analysis of colon from patients with complicated diverticulitis found an increase in the amount of activated CD68+ CD163+ macrophages, which also correlated with steroid intake, compared to those with chronic, recurrent diverticulitis." (PMID 32635383, 2020).
ductal carcinoma (3 papers, 2017 to 2025). "In the current study, we utilize this model to determine the effects of CD68+ macrophage depletion on tumor development in the murine mammary tumor virus polyoma middle T antigen (PyMT) transgenic mouse model of spontaneous breast ductal adenocarcinoma." (PMID 29220404, 2017). "In this study, the MacLow mouse model of doxycycline-inducible and selective CD68+ macrophage depletion was crossed with the murine mammary tumor virus (MMTV)-Polyoma virus middle T antigen (PyMT) mouse model of spontaneous ductal breast adenocarcinoma to generate the PyMT-MacLow line." (PMID 29220404, 2017). "CD68+ and CD163+ macrophages were found to be enriched in the invasive front of luminal ductal carcinomas." (PMID 37756565, 2023).
endotoxemia (3 papers, 2014 to 2020). "AICAR or compound C treatment decreased ALT, AST, and TNF levels in serum, reduced CD68 expression and MPO activity in liver tissue of mice with endotoxemia." (PMID 24475189, 2014). "Altogether, we assume that migration plays a predominant role in the observed phenotypes, as more CD68+ and CD8+ cells were found in the spleens of co-treated mice, suggesting macrophages and cytotoxic T cells to immigrate after AMD3100 administration in endotoxemia." (PMID 27716214, 2016).
esophageal adenocarcinoma (3 papers, 2012 to 2022). A malignant tumor with glandular differentiation arising predominantly from Barrett mucosa in the lower third of the esophagus. "In this study, a high proliferation index in oesophageal adenocarcinoma was associated with poor outcome (on univariate survival analysis) and was also associated with intra-tumoural macrophage infiltration (CD68+) and microvessel density (CD34+)." (PMID 22240784, 2012). "Tumour CD68+ infiltration of the oesophageal adenocarcinoma was directly associated with the Ki-67 proliferation index (P<0.001) as well as neo-adjuvant therapy (P<0.01)." (PMID 22240784, 2012). "Poorly differentiated oesophageal adenocarcinoma was directly associated with a LNR (P<0.001), inversely with the necrosis score (P<0.05) and directly with CD68+ infiltration (P<0.05)." (PMID 22240784, 2012). "It was of interest therefore, in this study, that CD68+ macrophages was strongly associated with CD8 + T lymphocytes and tumour proliferative index (Ki67) in oesophageal adenocarcinoma." (PMID 22240784, 2012). "Poorly differentiated oesophageal adenocarcinoma was directly associated with a LNR (P=0.001) and directly with CD68+ infiltration (P<0.05)." (PMID 22240784, 2012). "Recently, PD-1H was reported to be expressed with CD68 and CD4 in most cases of esophageal adenocarcinoma (EAC) and to have no reliable coexpression with CD8." (PMID 34950702, 2021).
Fibrolamellar carcinoma (3 papers, 2015 to 2022). "Fibrolamellar carcinoma has a distinctive morphology and immunophenotype, including cytokeratin 7 and CD68 co-expression." (PMID 28862261, 2018). "Currently, fibrolamellar carcinoma is diagnosed in most centers based on H&E morphology, often supplemented with immunostains for CK7 and CD68." (PMID 28862261, 2018). "It was reported that CD68 had a high positive rate in fibrolamellar carcinoma but was usually negative in scirrhous carcinoma, suggesting another strong differential marker." (PMID 35463333, 2022). "The fibrotic areas of the tumor also had the appearance of fibrolamellar carcinoma; however, fibrolamellar carcinomas are CD68-positive, and the fibrotic area in the present tumor was CD68-negative." (PMID 25928039, 2015). "We propose the best approach for the diagnosis of fibrolamellar carcinoma is based on compatible morphology with either molecular confirmation, or if not available, then confirmation by CK7 and CD68 immunohistochemistry." (PMID 28862261, 2018).
fibroxanthoma (3 papers, 2012 to 2023). "Dermatofibrosarcoma protuberans is negative for CD68, allowing differentiation from atypical fibroxanthoma and malignant fibrohistocytoma, and is also typically negative for S100, helping distinguish it from desmoplastic melanoma." (PMID 23199263, 2012).
giant cell arteritis (3 papers, 2016 to 2025). "Histopathological examination of the resected aortic wall revealed infiltration of giant cells positive for CD68, leading to the diagnosis of giant cell arteritis." (PMID 40486082, 2025). "Compartment-specific infiltration of CD68+ cells especially into the peritubular and the perivascular compartment was linked with TCMR with arteritis." (PMID 27285579, 2016). "Indeed, immunohistochemistry of temporal artery biopsies of giant cell arteritis (GCA) patients showed bright IST1 labeling of CD68+ macrophages and vimentin+ fibroblasts." (PMID 37200023, 2023). "In a random sample of 15 biopsies with TCMR without and with arteritis we found that 79.1% ± 2.3 of MHCII-HLA-DR+ cells were also CD68+ positive, whereas 39.3% ± 8.7 of Ki67+ cells were also CD68+." (PMID 27285579, 2016). "Additionally in the peritubular (p = 0.03) as well as the perivascular compartment (p = 0.004) aggressive TCMR with accompanying arteritis showed a significantly increased CD68 infiltration in contrast to TCMR without arteritis." (PMID 27285579, 2016).
glaucoma (3 papers, 2021 to 2025). Increased pressure in the eyeball due to obstruction of the outflow of aqueous humor. "In glaucoma, microglia/macrophages might transform into “ameboid” morphology and upregulate phagocytosis-associated protein CD68, antigen presentation molecule MHC-II, and other neurotoxic molecules, displaying the proinflammatory and phagocytic phenotypes." (PMID 35132339, 2022). "Overall, CD68+ cells were sparse (2–3 cells/section) in the glaucoma samples." (PMID 40581633, 2025). "CD68 and MHC-II expression were observed in the nerve fiber layer–ganglion cell layer after 15 days of unilateral laser-induced experimental glaucoma model." (PMID 33829024, 2021).
head and neck cancer (3 papers, 2022 to 2024). A primary or metastatic malignant neoplasm affecting the head and neck. "As for head and neck cancer, most of the previous research detected M2 macrophage by surface expression of CD68 and CD163." (PMID 36864443, 2023). "Altogether, our analysis indicated that CD8, FoxP3, and CD68 immunoscore was a strong, independent, and significant prognostic marker that could be introduced into the landscape of current tools to improve the clinical management of head and neck cancer patients." (PMID 35805132, 2022).